ECPAS (Ecm29 proteasome adaptor and scaffold)
Description:
Adapter/scaffolding protein that binds to the 26S proteasome, motor proteins and other compartment specific proteins. May couple the proteasome to different compartments including endosome, endoplasmic reticulum and centrosome. May play a role in ERAD and other enhanced proteolysis. Promotes proteasome dissociation under oxidative stress (By similarity).
Synonyms: ECM29; KIAA0368; FLJ22036
Tractability: PROTAC: UniProt records ubiquitination sites on it; ubiquitination databases record sites on it.
Gene: Protein-coding gene on chromosome 9 (111,360,685 to 111,484,745, reverse strand). Ensembl gene ENSG00000136813.
Subcellular location: Endoplasmic reticulum; Endoplasmic reticulum-Golgi intermediate compartment; Endosome; Cytoplasm, cytoskeleton, microtubule organizing center, centrosome; Nucleus; Endosome, multivesicular body; Cytoplasmic vesicle
Subcellular location (Human Protein Atlas): Nucleoplasm
Gene Ontology:
Molecular function: proteasome binding; protein binding; molecular adaptor activity
Biological process: ERAD pathway; proteasome assembly
Cellular component: centrosome; COPII-coated ER to Golgi transport vesicle; cytoplasmic vesicle; early endosome; endocytic vesicle; endoplasmic reticulum; endoplasmic reticulum-Golgi intermediate compartment; endosome; late endosome; membrane; multivesicular body; nucleoplasm; nucleus; trans-Golgi network; cytoplasm
Genetic constraint (gnomAD): Loss-of-function variants: 37 observed, 154.22 expected, observed/expected ratio (o/e) 0.24, 90% interval 0.18 to 0.32. The upper end of that interval is the gene's LOEUF score, 0.32, which puts it in group 1 of 6, group 1 being the genes least tolerant of losing a copy. Missense variants: 1,373 observed, 1,678.5 expected, observed/expected ratio (o/e) 0.82, 90% interval 0.78 to 0.86. Synonymous variants: 603 observed, 611 expected, observed/expected ratio (o/e) 0.99, 90% interval 0.92 to 1.06.
Homologues: Orthologues: chimpanzee ECPAS (99% identical), macaque ECPAS (99% identical), rabbit ECPAS (97% identical), dog ECPAS (97% identical), guinea pig ECPAS (96% identical), mouse Ecpas (96% identical), rat Ecpas (95% identical), pig ECPAS (95% identical), tropical clawed frog ecpas (78% identical), zebrafish ecpas (74% identical), Drosophila melanogaster CG8858 (33% identical), Caenorhabditis elegans ecps-1 (27% identical). Paralogues in human: GCN1 (17% identical).
Diseases named in the same sentence as ECPAS in open-access papers:
ECPAS is named in the same sentence as 11 diseases in open-access papers, as found by Europe PMC text mining. Sharing a sentence is not in itself a finding about the gene and the disease. The quoted sentences say what the papers report.
Infertility (1 paper, 2025). "Recent studies have demonstrated that mice deficient in both PA200 and ECPAS (double knockout) exhibit significantly reduced proteasome activity in the testes and epididymides, leading to infertility." (PMID 39859218, 2025).
ECPAS also shares sentences with these, for which no sentence is quoted: cancer (4 papers); tumor (2); Allergy (1); breast carcinoma (1); epilepsy (1); gastric cancer (1); infection (1); Obesity (1); orofacial cleft (1); prostate carcinoma (1).